ZDHHC15 (zDHHC palmitoyltransferase 15)
Description:
Palmitoyltransferase that catalyzes the addition of palmitate onto various protein substrates. Has no stringent fatty acid selectivity and in addition to palmitate can also transfer onto target proteins myristate from tetradecanoyl-CoA and stearate from octadecanoyl-CoA (By similarity). Palmitoylates IGF2R and SORT1, promoting their partitioning to an endosomal membrane subdomain where they can interact with the retromer cargo-selective complex. Thereby, regulates retrograde transport from endosomes to the Golgi apparatus of these lysosomal sorting receptors and plays a role in trafficking of lysosomal proteins. In the nervous system, catalyzes the palmitoylation of DLG4/PSD95 and regulates its synaptic clustering and function in synaptogenesis (By similarity). Could be involved in the differentiation of dopaminergic neurons and the development of the diencephalon (By similarity). Could also catalyze the palmitoylation of GAP43 (By similarity). Could also palmitoylate DNAJC5 and regulate its localization to the Golgi membrane (By similarity). Could also palmitoylate FYN as shown in vitro. May palmitoylate CALHM3 subunit of gustatory voltage-gated ion channels and modulate channel gating and kinetics.
Synonyms: FLJ31812; MRX91; DHHC15
Tractability: Antibody: UniProt predicts a signal peptide or a membrane-spanning region.
Gene: Protein-coding gene on chromosome X (75,368,427 to 75,523,502, reverse strand). Ensembl gene ENSG00000102383.
Subcellular location: Golgi apparatus membrane; Postsynaptic density
Subcellular location (Human Protein Atlas): Nuclear speckles; Cytosol
Gene Ontology:
Molecular function: palmitoyltransferase activity; protein binding; protein-cysteine S-palmitoyltransferase activity; protein-cysteine S-myristoyltransferase activity; protein-cysteine S-stearoyltransferase activity; zinc ion binding
Biological process: peptidyl-L-cysteine S-palmitoylation; protein localization to membrane; protein targeting to Golgi apparatus; positive regulation of dendrite development; protein localization to postsynapse; protein targeting to membrane; regulation of dendritic spine morphogenesis; synaptic vesicle maturation
Cellular component: Golgi apparatus; Golgi membrane; endoplasmic reticulum; postsynapse; postsynaptic density
Gene-disease validity (ClinGen):
ClinGen rates the evidence that ZDHHC15 causes each of these diseases.
X-linked complex neurodevelopmental disorder (X-linked): Disputed. A complex neurodevelopmental disorder that is transmitted via X-linked inheritance, and is characterized by intellectual disability, autism and epilepsy.
Homologues: Orthologues: chimpanzee ZDHHC15 (99% identical), macaque ZDHHC15 (99% identical), pig ZDHHC15 (98% identical), mouse Zdhhc15 (98% identical), rat Zdhhc15 (97% identical), guinea pig ZDHHC15 (95% identical), rabbit ZDHHC15 (84% identical), dog ZDHHC15 (74% identical), tropical clawed frog zdhhc15 (68% identical), zebrafish zdhhc15b (65% identical), Drosophila melanogaster CG1407 (43% identical), Caenorhabditis elegans dhhc-4 (36% identical), and 7 more. Paralogues in human: ZDHHC2 (57% identical), ZDHHC20 (55% identical), ZDHHC14 (21% identical), ZDHHC3 (21% identical), ZDHHC18 (20% identical), ZDHHC7 (19% identical), ZDHHC9 (19% identical), ZDHHC6 (18% identical), ZDHHC4 (17% identical), ZDHHC1 (17% identical), ZDHHC19 (16% identical), ZDHHC21 (16% identical), and 5 more.
Diseases named in the same sentence as ZDHHC15 in open-access papers:
ZDHHC15 is named in the same sentence as 28 diseases in open-access papers, as found by Europe PMC text mining. Sharing a sentence is not in itself a finding about the gene and the disease. The quoted sentences say what the papers report.
glioma (8 papers, 2021 to 2025). A benign or malignant brain and spinal cord tumor that arises from glial cells (astrocytes, oligodendrocytes, ependymal cells). "Expression of ZDHHC15 and its association with clinicopathological characteristics in glioma were validated by quantitative reverse transcription PCR (RT-qPCR) and immunohistochemical experiments." (PMID 37161425, 2023). "In conclusion, this study provides the first comprehensive analysis of the expression pattern of ZDHHC15 in glioma and establishes a clear association between high ZDHHC15 expression and malignant glioma phenotype." (PMID 37161425, 2023). "In this study, we found that ZDHHC15 expression is significantly associated with glioma malignant phenotypes." (PMID 37161425, 2023). "High expression of ZDHHC15 was positively associated with malignant phenotypes of glioma, particularly in WHO high-grade, IDH wild-type, 1p/19q non-codeletion, and recurrence subtypes." (PMID 37161425, 2023). "After validating the biological functions of ZDHHC15 in glioma, the underlying mechanism of ZDHHC15 in glioma was explored." (PMID 37161425, 2023). "Results showed that high ZDHHC15 expression was a high-risk indicator and an independent prognostic marker in patients with glioma." (PMID 37161425, 2023). "ZDHHC15 expression was significantly up-regulated in glioma and positively associated with malignant phenotypes." (PMID 37161425, 2023). "High expression of ZDHHC15 is associated with poor prognosis and ZDHHC15 is an independent prognostic biomarker in patients with glioma." (PMID 37161425, 2023). "High zDHHC15 expression was reported in glioma‐associated datasets, correlating with malignant phenotypes and poorer prognosis, an association confirmed by immunohistochemistry of glioma samples from human patients." (PMID 39429488, 2024). "Finally, we combined ZDHHC15 with common clinical risk factors to create a nomogram, which provides a model to quantitatively predict the prognosis of glioma patients." (PMID 37161425, 2023). "Subsequently, the association between ZDHHC15 expression level and glioma subtypes was explored." (PMID 37161425, 2023). "Moreover, gene correlation analysis in TCGA and CGGA databases also verified that ZDHHC15 was significantly associated with glioma cell proliferation- and migration-related genes." (PMID 37161425, 2023). "Enhancing glioma malignancy, ZDHHC15 emerged as a potential novel prognostic biomarker for glioma patients." (PMID 38532349, 2024). "zDHHC15 knockdown suppressed the proliferation and migration of U87 and U251 glioma cells, reducing cyclins B1/D and MMP2/9 expression, while zDHHC15 overexpression had opposite effects that were linked to STAT3 signaling." (PMID 39429488, 2024). "Our results demonstrate that ZDHHC15 plays a critical role in promoting the proliferation and migration of glioma cells via activation of the STAT3 signaling pathway." (PMID 37161425, 2023). "Collectively, these results reveal that ZDHHC15 is a prognostic biomarker in glioma patients and our nomogram can well predict the prognosis of glioma patients." (PMID 37161425, 2023). "Data from multiple glioma-associated datasets were used to investigate the expression profiles and potential biological functions of ZDHHC15 in glioma." (PMID 37161425, 2023). "To investigate the expression profiles of ZDHHC15 in glioma, we first compared the transcriptional levels of ZDHHC15 between glioma tissues and normal brain tissues." (PMID 37161425, 2023). "Glioma patients were divided into high- and low-expression groups based on the median expression level of ZDHHC15." (PMID 37161425, 2023). "Transwell assay results revealed that glioma cell migration rates were reduced following ZDHHC15 knockdown." (PMID 37161425, 2023). "Taken together, these results indicate that ZDHHC15 promotes the proliferation and migration of human glioma cells." (PMID 37161425, 2023).
glioma (continued). "To further confirm the prognostic value of ZDHHC15 in glioma patients, we compared the prognosis of glioma patients with high and low-ZDHHC15 expression in the CGGA database." (PMID 37161425, 2023). "In vitro experiments confirmed that knockdown of ZDHHC15 suppressed glioma cell proliferation and migration, while overexpression of ZDHHC15 promoted proliferation and migration." (PMID 37161425, 2023). "Consistent with above findings, glioma cells transfected with ZDHHC15 proliferated faster than cells transfected with the control vector." (PMID 37161425, 2023). "Results confirmed that ZDHHC15 mRNA level was higher in malignant phenotypes of glioma, including grade 4 glioma, GBM, and IDH wild-type glioma." (PMID 37161425, 2023). "As expected, the proliferation and migration of glioma cells overexpressed with ZDHHC15 were significantly inhibited after Stattic administration." (PMID 37161425, 2023). "Our findings suggest that ZDHHC15 promotes glioma malignancy and can serve as a novel prognostic biomarker for glioma patients." (PMID 37161425, 2023). "Subsequently, we explored the potential biological functions of ZDHHC15 in glioma through relevant enrichment analyses." (PMID 37161425, 2023). "Our gene set enrichment analysis (GSEA) results revealed a significant enrichment of the STAT3 signaling pathway in high ZDHHC15 expression in glioma." (PMID 37161425, 2023). "In this study, we first evaluated the mRNA and protein expression profile of ZDHHC15 in patients with glioma using both public datasets and clinical glioma samples." (PMID 37161425, 2023). "In gliomas, inactivation of ZDHHC15 blocked glioma cells proliferation by decreasing activation of Signal Transducer and Activator of Transcription 3 (STAT3) and knockdown of ZDHHC12 reduced the growth, migration, and invasion capabilities of glioma cells." (PMID 37759431, 2023). "Our results revealed that glioma cell proliferation and migration-related processes were highly enriched in the high ZDHHC15 expression group." (PMID 37161425, 2023). "Knockdown of ZDHHC15 inhibited glioma cell proliferation and migration, while overexpression of ZDHHC15 presented opposite effects on glioma cells." (PMID 37161425, 2023). "Patients with high-grade glioma exhibited higher protein levels of ZDHHC15 compared to low-grade glioma." (PMID 37161425, 2023). "To verify the functions and mechanisms of ZDHHC15 in the tumor progression of glioma cells, we performed ZDHHC15-siRNA knockdown and overexpression vector transfection experiments." (PMID 37161425, 2023). "Our data demonstrated that glioma patients with ZDHHC15 protein-positive expression had worse progression-free survival and overall survival." (PMID 37161425, 2023). "In this study, we found that ZDHHC15 mRNA levels were up-regulated in glioma tissues compared to normal brain tissues based on data from public databases and our clinical glioma samples." (PMID 37161425, 2023). "To further verify the biological functions of ZDHHC15, we established glioma cell lines that overexpressed ZDHHC15." (PMID 37161425, 2023). "Recent studies have confirmed a clear link between high zDHHC15 expression and the malignant glioma phenotype, and zDHHC15 plays a key role in promoting the proliferation and migration of glioma cells by activating the STAT3 signaling pathway." (PMID 38293675, 2023). "The results showed that glioma patients with higher ZDHHC15 expression exhibited poorer prognosis compared to that with lower ZDHHC15 expression." (PMID 37161425, 2023). "As expected, we observed poor overall survival in glioma patients with high ZDHHC15 expression compared to the low ZDHHC15 expression groups." (PMID 37161425, 2023). "GO enrichment analysis, KEGG analysis, GSEA analysis, CCK-8, EdU, transwell, and western blotting assays were performed to confirm the functions and mechanism of ZDHHC15 in glioma." (PMID 37161425, 2023).
glioma (continued). "In this study, we investigated the association between the DHHC family of proteins and local anesthetics in gliomas and found that ZDHHC15 was significantly downregulated in GSCs after treatment with prilocaine, procaine, lidocaine, or ropivacaine." (PMID 33541421, 2021). "ZDHHC15 levels in gliomas were elevated relative to the levels in the normal brain tissue and were positively correlated with the degree of malignancy." (PMID 33541421, 2021). "Researchers have also suggested that zDHHC15 may be a new prognostic biomarker for patients with glioma and that targeting zDHHC15 could provide a promising strategy for the treatment of glioma." (PMID 38293675, 2023). "Furthermore, the proportion of ZDHHC15 protein positive expression in IDH wild-type glioma was higher than that in IDH mutant glioma." (PMID 37161425, 2023). "Moreover, we performed Kaplan-Meier analysis and Cox progression analysis to explore the prognostic significance of ZDHHC15 in glioma patients." (PMID 37161425, 2023). "Finally, we employed Kaplan-Meier and Cox proportional hazards regression analyses to evaluate the prognostic value of ZDHHC15 in glioma patients based on clinical information and ZDHHC15 expression." (PMID 37161425, 2023). "In light of these results, we speculate that high expression of ZDHHC15 might play oncogenic roles in glioma." (PMID 37161425, 2023). "Based on our bioinformatics analysis and experimental results, we hypothesized that ZDHHC15 is a prognostic marker in glioma patients." (PMID 37161425, 2023). "Nevertheless, the expression patterns and underlying biological functions of ZDHHC15 in glioma have not been fully explored." (PMID 37161425, 2023). "Taken together, these results suggest that high ZDHHC15 expression may be involved in glioma cell proliferation and migration." (PMID 37161425, 2023). "Knockdown or overexpression of ZDHHC15 in glioma could regulate tumor cell proliferation and migration by targeting the STAT3 signaling pathway." (PMID 37161425, 2023). "Furthermore, the EdU assay results indicated a considerable restriction in the proliferation ability of glioma cells after ZDHHC15 knockdown." (PMID 37161425, 2023). "Additionally, we identified ZDHHC15 as an independent prognostic biomarker in glioma, and higher expression of ZDHHC15 predicted a poorer prognosis in glioma patients." (PMID 37161425, 2023). "Consistent with our previous finding, ZDHHC15 expression was significantly up-regulated in glioma." (PMID 37161425, 2023). "Further analyses of the glioma specimens revealed an important correlation between ZDHHC15 protein expression and Ki-67-positive cells, suggesting that ZDHHC15 might be involved in glioma cell proliferation." (PMID 37161425, 2023). "The results demonstrated that ZDHHC15 content was positively correlated with WHO grades in glioma." (PMID 37161425, 2023). "Conversely, overexpression of ZDHHC15 in glioma cell lines resulted in increased p-STAT3 levels." (PMID 37161425, 2023). "However, the biological functions and related mechanisms of ZDHHC15 in glioma remain poorly understood." (PMID 37161425, 2023). "We first compared ZDHHC15 expression in 60 glioma tissues, including pilocytic astrocytoma (PA, grade I; n = 6), oligodendrocytoma (OL, grade II, n = 18), anaplastic astrocytoma (AA, grade III; n = 15), and GBM (grade IV; n = 21), and eight normal brain tissue samples." (PMID 33541421, 2021). "In addition, because the expression of ZDHHC15 is positively correlated with the tumor grade of gliomas, ZDHHC15 can also be used as a useful marker for the diagnosis and prognosis of GBM." (PMID 33541421, 2021). "This further confirms our findings that ZDHHC15 silencing or local anesthetic treatment strongly induces differentiation, suggesting the existence of an additional mechanism by which ZDHHC15 inhibition could ameliorate the malignant phenotype in glioma." (PMID 33541421, 2021).
glioma (continued). "However, in our study, glioma patients with high ZDHHC15 expression showed poor overall survival." (PMID 37161425, 2023). "Targeting ZDHHC15 may be a promising therapeutic strategy for glioma." (PMID 37161425, 2023). "Besides glioma, we found that ZDHHC15 was aberrantly expressed in other tumors." (PMID 37161425, 2023). "Furthermore, we also investigated the molecular mechanism of ZDHHC15 in glioma progression." (PMID 37161425, 2023). "However, the function of ZDHHC15 in glioma progression is not well understood." (PMID 37161425, 2023). "Importantly, our findings suggest that ZDHHC15 may serve as a new prognostic biomarker for glioma patients, and targeting ZDHHC15 may offer a promising strategy for the treatment of glioma." (PMID 37161425, 2023). "Therefore, the purpose of this study is to investigate whether ZDHHC15 promotes the progression of glioma or serves as a novel prognostic biomarker for glioma patients." (PMID 37161425, 2023). "In our previous study, we found that ZDHHC4, ZDHHC9, ZDHHC12, ZDHHC15, and ZDHHC23 were abnormally expressed in glioma compared to normal brain tissues." (PMID 37161425, 2023). "We further verified these findings through the IHC assay, which showed that high ZDHHC15 protein expression was significantly correlated with WHO high-grade glioma and IDH wild-type glioma." (PMID 37161425, 2023). "Moreover, ZDHHC15 expression is significantly upregulated in glioma, promoting malignancy via the STAT3 signaling pathway, offering a novel prognostic biomarker for glioma patients." (PMID 40814339, 2025). "Furthermore, high ZDHHC15 expression was significantly associated with worse prognosis in patients with IDH1 wild-type and mutant glioma, 1p/19q non-codeletion glioma, MGMT promoter methylated and non-methylated glioma, and primary and recurrent glioma." (PMID 37161425, 2023). "However, unlike glioma, ZDHHC15 expression was downregulated in ovarian serous cystadenocarcinoma (OV), cervical squamous cell carcinoma and endocervical adenocarcinoma (CESC), and uterine corpus endometrial carcinoma (UCEC)." (PMID 37161425, 2023).
breast carcinoma (4 papers, 2020 to 2025). "To further investigate the clinical relevance of ZDHHC15 in cancer, we queried whole‐exome sequencing data of TCGA samples, which revealed several mutations in ZDHHC15, in individuals with either breast cancer or ovarian cancer." (PMID 39686664, 2025). "We found that ZDHHC15 expression is increased in breast cancer patient samples, and high ZDHHC15 expression is linked to poor prognosis, suggesting that ZDHHC15 could serve as a prognostic indicator for breast cancer patients." (PMID 39686664, 2025). "To further corroborate the clinical relevance of ZDHHC15 expression in breast cancer, we probed ZDHHC15 protein expression in tumor samples from patients with breast cancer (n = 55)." (PMID 39686664, 2025). "In addition, a significantly reverse correlation between ZDHHC15 and KIBRA expression was noted in tissue samples from breast cancer patients." (PMID 39686664, 2025).
glioblastoma (4 papers, 2021 to 2024). The most malignant astrocytic tumor (WHO grade IV). "ZDHHC15 has been identified as a promoter of glioblastoma malignancy and can serve as a novel prognostic biomarker for glioblastoma patients." (PMID 38300336, 2024). "In conclusion, our work emphasizes that ZDHHC15 is a candidate therapeutic target, and local anesthetics are potential therapeutic options for glioblastoma." (PMID 33541421, 2021). "Moreover, it weakened ZDHHC15 transcripts and reduced GP130 palmitoylation levels and membrane localization, thus impairing the growth and self-renewal of glioblastoma stem cells." (PMID 34389754, 2021).
X-linked intellectual disability (3 papers, 2019 to 2024). An X-linked intellectual deficiency in which not enough information is known, reported or published to indicate whether a gene causes non-syndromic or syndromic presentations. "For example, the functionally defective DHHC9 is related to X-linked intellectual disability and epilepsy and mutations in ZDHHC15 and ZDHHC8 are related to X-linked intellectual disability and schizophrenia, separately." (PMID 39598479, 2024). "ZDHHC15 is one of a number of genes on the X chromosome that is duplicated in patients with intellectual disability, and one report has identified the loss of a ZDHHC15 transcript in a female patient with non-syndromic X-linked intellectual disability." (PMID 31189538, 2019).